KDM5C (lysine demethylase 5C)
Diseases named in the same sentence as KDM5C in open-access papers (continued):
Sharing a sentence is not in itself a finding about the gene and the disease.
breast cancer (continued). "Indeed, overexpression of the escape genes KDM5C, KDM6A and DDX3X is associated with cancer development, proliferation, invasion and metastasis in certain type of cancers such as breast cancer." (PMID 28686623, 2017). "Both KDM5C's activator and repressor nature contribute to its oncogenic function in ER‐positive breast cancer development, and therefore it might serve as a potential drug target in ER‐positive and endocrine therapy‐resistant breast cancer." (PMID 33977073, 2021). "This has been demonstrated for other KDM5 family members, such as KDM5C, which requires its interactions with ERα and ZMYND8 to activate estrogen target genes to promote breast cancer cell growth." (PMID 41308413, 2025). "We established stable expression cell lines of HA-KDM5C and HA-TRIM11 in MDA-MB-231 breast cancer cells, and verified the function of exogenous expressed TRIM11 on down-regulating KDM5C." (PMID 36192394, 2022). "TRIM11 and KDM5C stable knockdown cell lines were also established in MDA-MB-468 and ZR-75-30 breast cancer cells." (PMID 36192394, 2022). "In breast cancer patient tissues, TRIM11 is highly expressed and KDM5C is lower expressed, and their expression is negatively correlated." (PMID 36192394, 2022). "Suppression of migration and invasion by ZMYND8 in breast cancer cells is through cooperation with KDM5C and modulation of SA100, as knockout of ZMYND8 or KDM5C can de-repress S100A." (PMID 33670804, 2021). "In ZR-75-30 breast cancer cells, ZMYND8 promotes the recruitment of KDM5C to the super-enhancer region, shown by the co-binding of ZMYND8 and KDM5C to 88.7% super-enhancers." (PMID 33670804, 2021). "We focused on studying the interaction between KDM5C and ZYMND8 and their contributions to estrogen‐induced gene transcriptional activation due to the following reasons: i) The role of KDM5C and ZYMND8 in breast cancers has been controversial." (PMID 33977073, 2021). "Taken together, our data demonstrated that KDM5C can activate estrogen/ERα‐target genes to promote cell growth as well as repress type I IFNs and ISGs to escape from immune surveillance, both of which might contribute to its oncogenic function in ERα‐positive breast cancers." (PMID 33977073, 2021). "Our findings showed that ZMYND8 is instrumental in recruiting corepressors, KDM5C, and EZH2 onto their target promotors to regulate tumor-genes in breast cancer." (PMID 33323928, 2020). "Our data show that KDM5C is also involved in the regulation of inflammation genes, which suggest that TRIM11-mediated KDM5C degradation is probably also involved in the immune response in breast cancer." (PMID 36192394, 2022). "It is reported that KDM5C activates estrogen receptor alpha (ERα) target genes while inhibiting type I interferon (IFN) and interferon stimulating genes to promote the growth of ERα-positive breast cancer cells and tumorigenesis." (PMID 35248043, 2022). "These suggest that in breast cancer tissues, TRIM11 probably mainly regulates KDM5C in nuclei." (PMID 36192394, 2022). "The results suggest that TRIM11 selectively regulates KDM5C stability in breast cancer cells and HEK293T, but not other tested cell lines." (PMID 36192394, 2022). "High expression of KDM5C was correlated with poor prognosis in ER‐positive, but not ER‐negative, breast cancer patients." (PMID 33977073, 2021). "Here, it is reported that KDM5C, a repressive histone demethylase, unexpectedly activates estrogen receptor alpha (ERα)‐target genes, and meanwhile suppresses type I interferons (IFNs) and IFN‐stimulated genes (ISGs) to promote ERα‐positive breast cancer cell growth and tumorigenesis." (PMID 33977073, 2021). "We propose that combination therapy with inhibitor targeting KDM5C enzymatic activity and KDM5C/ZMYND8 interaction or ERα antagonist would be efficacious in battling and/or provide an additional therapeutic adjunct for ER‐positive and endocrine therapy‐resistance breast cancers." (PMID 33977073, 2021).
breast cancer (continued). "Both miRNAs are down-regulated in several breast cancer cell lines compared with nontumorigenic human mammary epithelial cell line MCF10A, consistent with the higher expression levels of KDM5B and KDM5C in these cancer cells." (PMID 30080846, 2018).
clear cell renal cell carcinoma (16 papers, 2011 to 2025). "In von Hippel-Lindau-deficient clear cell renal cell carcinoma cells, the knockdown of KDM5C restored the H3K4me3 level and promoted growth of xenograft tumors in nude mice." (PMID 38216914, 2024). "Loss-of-function mutations in KDM5C have been identified in several types of cancers, including clear cell renal cell carcinoma (ccRCC), and KDM5C is thought to be a tumor suppressor gene." (PMID 35805040, 2022). "KDM5C is commonly mutated in clear cell renal cell carcinomas (ccRCC) in men but rarely in women." (PMID 39955388, 2025). "KDM5 proteins as tumour suppressors: The KDM5C protein acts as a tumour suppressor in clear cell renal cell carcinomas (ccRCC), where the incidence in males-to-females is 2:1, and mutations in KDM5C are high." (PMID 35406676, 2022). "The von Hippel-Lindau tumor-suppressor protein regulates gene expression and tumor growth via the histone demethylase JARID1C/KDM5C/SMCX in clear-cell renal cell carcinoma." (PMID 23922798, 2013). "Although inhibition of KDM5C could have adverse effects on neuronal circuits or promote tumor formation in clear cell renal carcinoma and cervical cancer, KDM5C was also shown to have oncogenic roles in prostate cancer." (PMID 30080846, 2018). "Whereas VHL inactivation is a primary event in clear cell renal cell carcinoma (ccRCC), the precise mechanism(s) of how this interacts with the secondary mutations in tumor suppressor genes, including PBRM1, KDM5C/JARID1C, SETD2, and/or BAP1, remains unclear." (PMID 30355451, 2018). "Combined analysis of three recent large-scale clear cell renal cell carcinoma (CCRCC) mutation sequencing projects identified a significantly increased mutation frequency of PBRM1 and the X chromosome encoded KDM5C in tumors from male patients and BAP1 in tumors from female patients." (PMID 26484545, 2015).
epilepsy (13 papers, 2012 to 2025). A brain disorder characterized by episodes of abnormally increased neuronal discharge resulting in transient episodes of sensory or motor neurological dysfunction, or psychic dysfunction. "KDM5C gene silencing leads to down-regulation of SCN2A, CACNA1B; CACNA1H; SCL4A3, SLC18A1, and SLC6A12, All of these KDM5C target genes have been linked to neurological disorders such as epilepsy, autism or schizophrenia." (PMID 39948613, 2025). "Mutations in the X chromosome demethylase KDM5C are associated with X-linked intellectual disability and epilepsy." (PMID 38764741, 2024). "For instance, a regulatory pathway associated with X-linked ID and epilepsy links KDM5C to polyalanine expansions in ARX, suggesting that the length of polyalanine tracts may correlate with the severity of X-linked ID and/or epilepsy." (PMID 39408661, 2024). "Interestingly, among multiple CRF genes, only SMARCA2, SMARCB1, ACTL6B and KDM5C have been previously associated with epilepsy, and some other members of this cluster (e.g., SMARCC1, SMARCC2, SMARCA4 and WRD5) are only cursorily mentioned among epilepsy candidate genes." (PMID 36982355, 2023). "Many MRXCSCJ patients have epilepsy, and Kdm5c-KO male mice have an increased propensity for kainic acid-induced seizures." (PMID 36831303, 2023). "Overall, these results suggest the potential use of KDM5C as a molecular stratification factor in GBM, with a particular attention for patients with epilepsy and IDH1/2 mutations." (PMID 36142158, 2022). "Variants in KDM5C are implicated in an X-linked NDD with mild to severe ID, epilepsy, short statue, mild facial dysmorphism including large ears, and hypogonadism (MRXSJ [MIM #300534]), partly mirroring the phenotype observed in males with BFLS41–44." (PMID 33149206, 2020). "For instance, Kdm5c plays a vital role in brain development in the mouse, and a mutant KDM5C of its homologous gene in human can lead to mental retardation, epilepsy and autistic spectrum disorder." (PMID 28095777, 2017).
prostate carcinoma (12 papers, 2015 to 2025). A carcinoma that arises from epithelial cells of the prostate gland. "This enzyme belongs to the KDM5 subfamily, which was found to be upregulated in prostate cancer patients and to be frequently mutated in pediatric AML specimens as well as in human MM cell lines, supporting the idea of KDM5C functioning as an oncogenic driver." (PMID 35053409, 2022). "Taken together, our results indicate the potential to therapeutically target KDM5C either alone or in combination with Akt/mTOR-inhibitor in prostate cancer patients by targeting the EMT signaling pathways." (PMID 35454801, 2022). "The putative role of KDM5C as an oncogene in cancer development is supported by the observations that KDM5C is highly expressed in prostate cancer and other malignant tumors relative to normal tissues." (PMID 26503415, 2015). "We establish that stable clones silence KDM5C in prostate cancer cells." (PMID 35454801, 2022). "KDM5C has also been observed to be overexpressed and promote tumor growth in prostate cancer." (PMID 32714863, 2020). "In our analysis, twelve histone demethylases showed gene upregulation in prostate cancers, of which six (KDM1A, KDM4B, KDM5B, KDM5C, KDM7A, and PHF8) were in line with previous reports." (PMID 36776320, 2023). "As an oncogene, KDM5C is found to be upregulated and promotes cell proliferation and metastasis in HCC and prostate cancer." (PMID 32714863, 2020). "KDM5 family members are H3K4 demethylases; JARID1B (KDM5B) is upregulated in prostate cancer tissues and acts as an AR coactivator, while JARID1C (KDM5C), overexpressed in prostate cancer, emerged as a predictive marker for therapy failure in patients after prostatectomy." (PMID 29888169, 2018).
X-linked intellectual disability (12 papers, 2014 to 2025). An X-linked intellectual deficiency in which not enough information is known, reported or published to indicate whether a gene causes non-syndromic or syndromic presentations. "A previous study found promoter CpG sites with reduced DNA methylation in the blood of male patients with X-linked intellectual disability and mutations in Kdm5c." (PMID 38318533, 2024). "KDM5C, which has a unique role in neural development, harbors a number of mutations adjacent to its accessory domains that cause X-linked intellectual disability (XLID)." (PMID 36495919, 2023). "Multiple human genetic studies have demonstrated that human BRWD3 and KDM5C mutations underlie X-linked intellectual disability." (PMID 37034668, 2023). "Our findings define functional roles of the ARID and PHD1 domains in the regulation of KDM5C and provide rationale for disruption of this regulation by mutations in X-linked intellectual disability." (PMID 36495919, 2023). "For instance, KDM5C mutations are frequently found in X-linked intellectual disability, linking KDM5C function to developmental regulation." (PMID 35899196, 2022). "The lysine specific demethylase 5C (KDM5C) is a cause of X-linked intellectual disability (ID) in males (Mental retardation, X-linked, syndromic, Claes-Jensen type; MIM# 300534)." (PMID 34530748, 2021). "In conclusion, this study reports a specific methylation “epi-signature” resulting from loss of function mutations in the KDM5C gene that can be used to diagnose males with X-linked intellectual disability and asymptomatic female carriers." (PMID 29456765, 2018). "To-date, 22 mutations in the human KDM5C paralog have been found in patients with X-linked intellectual disability." (PMID 25329053, 2014). "Pathogenic variants in KDM5C are a cause of X-linked intellectual disability in males." (PMID 34530748, 2021). "Among the disease-causing genes associated with X-linked intellectual disability (XLID), KDM5C is one of the most frequently mutated ones." (PMID 39948613, 2025).
gastric cancer (8 papers, 2020 to 2024). A primary or metastatic malignant neoplasm involving the stomach. "In order to investigate the role of KDM5C in the metastatic potential of gastric cancer cells, KDM5C was knocked down and its expression was enhanced in the MKN-45 cell line." (PMID 37202737, 2023). "This study also screened the expression of KDMs in tumor and normal samples, and identified KDM5C as highly expressed in gastric cancer." (PMID 37202737, 2023). "Recent studies have found that KDM5C is also highly expressed in ER-positive primary gastric cancer, regulated by ER and HIF1, and can significantly promote the proliferation, migration and invasion of gastric cancer cells." (PMID 35493099, 2022). "There need to be more studies of KDM5C in regulation of tumor microenvironment in gastric cancer." (PMID 37202737, 2023). "Considering that KDM5C was upregulated in gastric cancer based on transcriptomic data, the higher expression of KDM5C in gastric cancer was validated using seven paired tumor-normal tissues through western blotting." (PMID 37202737, 2023). "MSI-H is common in digestive cancer including colorectal cancer and gastric cancer, while KDM5C alterations were more common in endometrial and renal cell carcinoma, indicating the predictive value of MSI-H and KDM5C alterations is not overlapped." (PMID 33953726, 2021).
autism (7 papers, 2011 to 2025). Persistent deficits in social interaction and communication and interaction as well as a markedly restricted repertoire of activity and interest as well as repetitive patterns of behavior. "KDM5C has been linked to several sex-dependent phenotypes including X-linked intellectual disability (XLID), autism, X inactivation, adiposity, immune response, and cancer." (PMID 37018401, 2023). "In men and male mice, variants of KDM5C cause XLID with short stature, aggressive behavior, and autism." (PMID 37018401, 2023).
cervical cancer (7 papers, 2018 to 2022). A primary or metastatic malignant neoplasm involving the cervix. "For instance, increased demethylation of H3K4me3 by KDM5C has been reported to inhibit the expression of LINC000231 that was related to the pathogenesis of cervical cancer." (PMID 34266408, 2021). "E6 hijacked KDM5C/lnc_000231/miR‐497‐5p/CCNE1 signalling pathway is promising targets for cervical cancer treatment in the future." (PMID 32818316, 2020). "E6 hijacked KDM5C/lnc_000231/miR‐497‐5p/CCNE1 signalling pathway is a promising target for cervical cancer treatment in the future." (PMID 32818316, 2020). "Previous studies showed that E6 interacts with KDM5C in cervical cancer cells and promotes KDM5C degradation in an E3 ligase E6AP‐ and proteasome‐dependent manner." (PMID 32818316, 2020). "The structure and function of KDM5C is very similar to the highly tumourogenic KDM5A and KDM5B; it is overexpressed in cervical cancer and increased expression of this gene is associated with disease severity." (PMID 31766427, 2019). "Coincidentally, our recent study showed that high-risk human papillomavirus (HPV) protein degraded the KDM5C protein and promoted cervical cancer progression 24, again reinforcing the idea that KDM5C can play a protective role in the prevention of female malignancies." (PMID 34522206, 2021). "In cervical cancer, KDM5C represses the expression of the EGFR to function as a tumor suppressor." (PMID 32714863, 2020).
Cognitive impairment (7 papers, 2008 to 2025). Abnormal cognition is characterized by deficits in thinking, reasoning, or remembering. "In addition, the clinical phenotype associated with mutations in the KDM5C gene shows a degree of variability with regard to the facial dysmorphism and cognitive impairment, making the diagnosis difficult by merely relying on the clinical findings." (PMID 29456765, 2018). "In light of our analyses, it is possible that oxidative stress-mediated cellular damage may contribute to the intellectual impairment and other phenotypes associated with by loss of KDM5C in humans such as seizures." (PMID 25329053, 2014). "Normally, XCI balances gene dosage, but in KS, genes such as GTPBP6 (guanosine triphosphate binding protein 6), EIF2S3 (eukaryotic translation initiation factor 2 subunit 3), and KDM5C (Lysine(K)‐specific demethylase 5C) escape inactivation and are overexpressed, contributing to cognitive deficits." (PMID 40018421, 2025).
hepatocellular carcinoma (7 papers, 2015 to 2025). A malignant tumor that arises from hepatocytes. "Taken together, these results show that BMP7 mediates KDM5C-induced migration and invasion in hepatocellular carcinoma cells." (PMID 26503415, 2015). "In contrast, KDM5C and KDM6A have been shown to exhibit tumor-suppressive effects (e.g., metabolic repression and inhibition of cell proliferation) in intrahepatic cholangiocarcinoma and hepatocellular carcinoma, respectively." (PMID 41301905, 2025).
renal carcinoma (7 papers, 2011 to 2024). A carcinoma arising from the epithelium of the renal parenchyma or the renal pelvis. "We first measured the ratio of renal cancer cells in each phase of the cell cycle, and the results indicated that the loss of both KDM5C and YY1 caused an increased ratio of 769-P tumor cells arrested in the G2/M phase." (PMID 39433896, 2024). "In addition, a systematic sequencing approach in human renal cancers has identified UTX (KDM6A), Jarid1C (KDM5C) as genes mutated in renal carcinoma." (PMID 21924352, 2012). "This is similar to the distinct TMPRSS-ERG fusions identified in several regions of the primary prostate tumour and alterations of SETD2, PTEN and KDM5C in renal cancer." (PMID 28961847, 2017). "In addition, we also performed the semi-endogenous Co-IP with YY1 and KDM5C-Flag in 769-P renal cancer cell lines." (PMID 39433896, 2024). "Previous studies reported KDM5C is required for proper DNA replication at early origins and its alterations could lead to genomic instability in sporadic renal cancer." (PMID 33953726, 2021). "To achieve this goal, we first selected human kidney proximal tubular epithelial cell line (HK-2), and several renal cancer cell lines (ACHN, 769-P and RCC4) with different KDM5C and YY1 protein expression levels, as described in our previous studies." (PMID 39433896, 2024).